ERBB2 (erb-b2 receptor tyrosine kinase 2)
Diseases named in the same sentence as ERBB2 in open-access papers (continued):
Sharing a sentence is not in itself a finding about the gene and the disease.
gastric cancer (continued). "In the same way that detection of ERBB2-positivity by IHC or FISH modifies treatment in breast and gastric cancer, a similar adjuvant treatment may exist in the future for non-small cell lung cancers." (PMID 37363568, 2023). "Dysregulation of the HER2/neu (ERBB2) receptor tyrosine kinase is another noteworthy molecular aberration in serous EC considering that HER2 is a proven druggable molecular target in other cancers, such as breast or gastric cancer." (PMID 34036097, 2021). "Moreover, we examined GPC3 and ERBB2 expression levels in gastric cancer (GC)." (PMID 34975912, 2021). "Together, ERBB2, VIM, and PSMB8 may be effective targets in gastric cancer, but more experimental investigations and clinical trials are needed." (PMID 31949544, 2019). "Currently, surgery, chemotherapy and targeted therapy, including Erb-B2 receptor tyrosine kinase 2 (ERBB2) and vascular endothelial growth factor receptor (VEGFR) inhibitors, are the effective gastric cancer therapies, but the long-term survival rate remains unsatisfactory." (PMID 31118109, 2019). "We further report two cases of advanced gastric cancer patients, one treatment naïve, and the other having failed four lines of therapy, whose ERBB2 CNAs were identified by cfDNA and derived clinical benefit from HER2-based therapies." (PMID 31019892, 2019). "However, the small sample size made the statistical power limited and larger sample size studies relevant to HER2/c-erbB-2, EGFR protein expression in gastric carcinoma and its clinical significance were needed to further discussion it correlation." (PMID 33817143, 2019). "It has been shown that ErbB2 is transactivated by GDF15 in human breast and gastric cancer cells." (PMID 29636108, 2018). "HER-2 over-expression and/or ErbB2 gene amplification (20% of gastric cancer cases) represents a negative predictor of response to chemotherapy and a positive factor to anti-HER2 agents." (PMID 29986466, 2018). "Together with our finding that HER2-depletion indeed decelerates the growth rate of MKN45 cells, these data collectively underpin the importance of SOS1 expression in the ErbB2/HER2 signaling cascade and in the maintenance of gastric cancer cell lines." (PMID 29686309, 2018). "By contrast, expression of ERBB2 correlates with the expression of FUT3, the main fucosyltransferase responsible for the biosynthesis of the related antigen sialyl Lea (sLea) in gastric cancer specimens." (PMID 29462882, 2018). "As expected, the miR-1296-5p expression was suppressed in a majority of ERBB2-positive gastric cancer samples compared to ERBB2-negative gastric cancer samples." (PMID 28099468, 2017). "This down-regulation in ERBB2-positive breast and gastric cancer tissues was more obvious than that in ERBB2-negative breast and gastric cancer tissues." (PMID 28160563, 2017). "In ERBB2-positive gastric cancers, the miR-1296-5p expression was suppressed in a majority of metastatic lymph node tissues compared to non-metastatic gastric cancer samples." (PMID 28099468, 2017). "In summary, this is the first report showing that APIP displays a pivotal oncogenic activity by binding to ERBB3 to stimulate the formation of ERBB3/ERBB2 heterodimer, leading to amplification of HRG-mediated signaling involved in cell proliferation and tumorigenesis in gastric cancer." (PMID 26942872, 2016). "If these findings can be translated into gastric cancer settings, patients with high expression of MET, FGFR1 and ERBB2 may exhibit EGFR therapeutic resistance." (PMID 27738318, 2016). "IHC staining for breast metastasis from gastric cancer is usually negative for ErbB-2, ER, PR, and GCDFP-15, but positive for epithelial markers like CEA, CK7, and CK20." (PMID 25890325, 2015). "In addition, miR-375 was shown to suppress ERBB2 expression by directly targeting the 3′-UTR of ERBB2, and overexpression of miR-375 was shown to partially inhibit gastric cancer cell proliferation through the ERBB2 pathway." (PMID 24926380, 2014).
gastric cancer (continued). "We analyzed the cellular localization of erbB2 and flotillins in SGC-7901 gastric cancer cell." (PMID 23658725, 2013). "The fluorescent signals from the HER2 (ERBB2; NEU or CD340) DNA probe, an important marker in breast and gastric cancer diagnostics, could already be observed at t = 0 minutes in EC buffer." (PMID 22911704, 2012). "Furthermore, a higher frequency of ERBB2 and EGFR gene amplification is present in gastric cancer patients with lymph node metastases." (PMID 21689422, 2011). "Therefore, in the present study, we utilized fluorescence in situ hybridization (FISH) to assess amplification of the ERBB2 and EGFR genes in gastric cancer patient samples." (PMID 21689422, 2011). "This study evidences previously observed perturbations of the KRAS, ERBB2, EGFR, MET, PIK3CA, FGFR2 and AURKA genes in gastric cancer and suggests some of the targeted therapies approved or in clinical development would be of benefit to 11 of the 50 patients studied." (PMID 21781349, 2011). "On the basis of these earlier observations, we wanted to determine whether MUC4 exerts its function through regulating ErbB2 expression and activation in AGS-MUC4 gastric cancer cells." (PMID 18781152, 2008). "More recently it has been reported that, in human MKN7 gastric cancer cells, HRGβ1 can also circumvent the antiproliferative action of the selective EGFR-TKI CGP59326 through promotion of erbB3/erbB2 heterodimerization and activation of the PI3K signalling pathway." (PMID 17686159, 2007). "In contrast with breast and gastric cancer, no established ERBB2 testing guidelines exist for EC." (PMID 39235791, 2024). "Indeed, although several clinical studies have explored the effects of targeted therapies alone or in combination with chemotherapies for gastric cancer, currently only ramucirumab (anti-VEGFR2) and trastuzumab (anti-ErbB2) have been approved as gastric efficient targeted drugs." (PMID 35372019, 2022). "Three receptor tyrosine kinases (RTKs), MET, ErbB2, and FGFR2, have been widely studied in gastric cancer (GC)." (PMID 35884507, 2022). "Amplification of HER2 gene (ERBB2) and overexpression of HER2 protein on cancer cells are found in 10–26% of gastric cancer (GC) and esophagogastric junction cancer (EGJC)." (PMID 33198632, 2020). "However, the potential effect of ERBB2 and its downstream pathway engaged in the modulation of cell migration in gastric cancer has not yet been reported." (PMID 28099468, 2017). "In view of the fact that ERBB2 was the target gene of miR-1296-5p, we speculated that miR-1296-5p has negative correlation with ERBB2 in gastric cancer tissues." (PMID 28099468, 2017). "Notably, the expression level of miR-375 was significantly lower in ERBB2-positive gastric cancer tissues as compared with ERBB2-negative gastric cancer tissues." (PMID 24926380, 2014). "By contrast, direct repeat amplification has been observed in cancer cells taken directly from patients, e.g., in esophageal adenocarcinoma bearing ERBB2 amplifications, and in gastric carcinoma bearing amplification of the 17q21 locus, which is not linked to common fragile sites." (PMID 25061979, 2014). "Although the ERBB2 gene, a well-known oncogene that is often amplified in gastric cancer, was included in this list, the roles of the most of the genes in the Table have not been studied in gastric cancer." (PMID 22591714, 2012). "Co-expression of ERBB2 and EGFR may have synergistic effects on the progression of gastric cancer." (PMID 21689422, 2011). "However, the clinical significance of ERBB2 amplification/overexpression in gastric cancer patients is still not clear, because most studies had neither follow-up data nor statistical power for that purpose." (PMID 19156142, 2009). "Our survival analysis showed that ERBB2-amplifying expansive carcinomas have worse prognosis than those with the same growth pattern lacking that genetic alteration (P=0.011), which we did not observe in infiltrating gastric carcinomas (P=0.863)." (PMID 19156142, 2009).
gastric cancer (continued). "Genomic hybridization analysis using cDNA microarrays detected the co-amplification of the ERBB2 and GRB7 genes in a series of human gastric cancer xenographs, primary tumors and tumor cell lines, although overexpression was apparent for ERBB2 but not for GRB7." (PMID 19424485, 2008). "In vitro binding of [3H]cholesteryl ether ([3H]Chol ether) labelled anti-erbB-2 conjugated liposomes to N-87 cells (erbB-2-positive human gastric carcinoma) was compared with the binding of non-targeted liposomes and indicated a 16-fold increase in binding for the targeted liposomes." (PMID 8956788, 1996). "In the gastrointestinal tract, studies have been conducted on ERBB2-mutant gastric cancer (GC) and colorectal cancer (CRC); however, none have comprehensively examined ERBB2-mutant esophageal adenocarcinoma (EAC)." (PMID 37754252, 2023). "Thus, the same may be said of co-amplification of ERBB2 and TOP2A in gastric cancer." (PMID 28915696, 2017). "Ensuing clinical trials revealed only modest patient efficacy, and many ERBB2-positive gastric cancer (GC) patients failed to respond at all (i.e., were inherently recalcitrant), or succumbed to acquired resistance." (PMID 26955870, 2016). "Although the addition of trastuzumab to chemotherapy significantly prolonged survival in patients with ERBB2-overexpressing breast or gastric cancers, these clinical benefits failed to translate in improved survival of patients with ERBB2-overexpressing non-small cell lung cancers (NSCLCs)." (PMID 23630663, 2013). "On the other hand, ERBB2 amplification detected by NGS was not totally equal to the status of HER2-positive detected by IHC in breast and stomach cancer." (PMID 35911441, 2022). "Although Erb-B2 receptor tyrosine kinase 2 (ERBB2/human epidermal growth factor receptor 2) plays a significant therapeutic role in breast and gastric cancers, there are no licensed ERBB2-targeted therapies for metastatic CRC." (PMID 36291943, 2022). "Her2 (ERBB2) is one of the most established therapeutic targets in breast and gastric cancer but agents targeting Her2 have not yet demonstrated anti-tumor activity in MIBC." (PMID 28205537, 2017). "In this study, ERBB2/HER2 alteration rates were similar to the gastric cancer cohort (9.5% genomic alteration rate), however 69% of these alterations were amplifications in gastric cancer, as opposed to just 23% in SBAs." (PMID 35267592, 2022). "The amplification and overexpression of ERBB2 (or HER2/neu) lead to several intracellular signals such as the activation of the MAPK signaling pathway and is very common in intestinal-type but not in diffuse-type gastric carcinomas." (PMID 32023907, 2020). "However, with the exception of the ErbB2-targeting antibody, targeting agents, including PI3K/Akt/mTOR inhibitors, have not been approved for treatment of patients with gastric carcinoma." (PMID 25003395, 2014). "In addition to ERBB2 and PERLD1, the TRAC analysis also identified five novel genes, CYP3A4, ENAH, MMP9, PTPRA, and OSMR, which have not been reported as gained and overexpressed in gastric cancer before." (PMID 20187983, 2010).
ovarian carcinoma (877 papers, 1996 to 2026). A malignant neoplasm originating from the surface ovarian epithelium. "The overexpression of EGFR and/or ErbB2 frequently occur in human ovarian cancer; this is associated with more aggressive tumor behavior and poorer patient outcomes." (PMID 36770705, 2023). "We highlighted a leading protein–protein interaction (PPI) network underlying breast, endometrial, and ovarian cancers centered on the oncogene Erb-B2 Receptor Tyrosine Kinase 2 (ERBB2)." (PMID 35740327, 2022). "ERBB2 overexpression occurs in many kinds of human cancers such as breast and ovarian cancers, and its association with poor prognosis in these cancers has been widely proven." (PMID 35402217, 2022). "Obviously, the genes generally mutated in ovarian cancer were more amplified in chr17 in HG3_M than in the primary tumors on both sides, such as the ERBB2 and HOXB-AS3 genes, which are generally mutated in ovarian cancer." (PMID 35935940, 2022). "Our previous integrated computational analyses discovered a leading protein–protein interaction (PPI) network underlying breast, endometrial, and ovarian cancers, that is centered on ERBB2." (PMID 35740327, 2022). "Overexpression and/or mutations in EGFR and ERbB2 are well documented in ovarian cancer and have therapeutic implications." (PMID 36140319, 2022). "BRAF V600E and PIK3CA E542K were predominantly associated with thyroid cancer and ovarian cancer, respectively, whereas ERBB2 amplification, BRCA1/2 variant, and KRAS G12C were widely detected across various cancer types." (PMID 36088851, 2022). "On the other side, the mutational frequency of ERBB2 was the lowest in kidney cancer, sarcoma, liver cancer, and ovary cancer." (PMID 35911441, 2022). "The constitutive activation of HER2 (erbB2, neu) based on overexpression and/or mutation has been observed in various cancers, including ovarian carcinoma, and has been linked to disease progression, resistance to treatment and poor prognosis." (PMID 33572976, 2021). "Examples include human epidermal growth factor receptors EGFR (HER1) and ERBB2 (HER2) whose overexpression in head and neck, ovarian, cervical, bladder and esophageal cancer (EGFR), or breast and ovarian cancer (HER2) is associated with poor prognosis." (PMID 34201655, 2021). "Three networks (Network #1, #5, and #12) were linked to EGFR/ERBB2 signaling pathways that are well-known to have a major role in ovarian cancer." (PMID 33228226, 2020). "The most provocative and exciting results pertain to the oncoprotein HER2 (ERBB2 oncogene), whose overexpression is widely associated with breast and ovarian cancer." (PMID 31997977, 2020). "ErbB2 (also known as HER2) expression in ovarian cancer is associated with advanced stage, higher recurrence frequency, shorter survival time, and lower sensitivity to platinum-based chemotherapy." (PMID 22481926, 2012). "The ERBB2 proto-oncogene encodes a transmembrane protein tyrosine kinase receptor involved in the development and progression of many cancers including ovarian cancer." (PMID 23189165, 2012). "Indeed, the current Bouquet-ENGOT-gyn2 rare ovarian cancers basket trial (ClinicalTrials.gov identifier: NCT04931342) includes an arm for ERBB2/HER2-amplified/mutated cases for treatment with trastuzumab emtansine." (PMID 36222710, 2022).
ovarian carcinoma (continued). "Finally, we found ovarian cancer cell lines with ErbB2 mutations or overexpression to be particularly sensitive to Grb2 downregulation." (PMID 32754300, 2020). "Given our findings in ErbB2 mutated or amplified ovarian cancer cell lines, we hypothesized that Grb2 was a critical mediator of oncogenic signaling in uterine carcinomas." (PMID 32754300, 2020). "Moreover, the EGFR or ERBB2 overexpression could cause resistance to ovarian cancer cell death and increase tumor-initiating capacity." (PMID 35889396, 2022). "HER2 (ERBB2) is overexpressed in subsets of ovarian cancers, particularly high-grade serous and mucinous histologies, contributing to aggressive behavior 52-54." (PMID 41438580, 2026). "ERBB2 can be involved in the biological process of tumors in lung, breast, and ovarian cancers 28-30." (PMID 38911367, 2024). "Tyrosine kinase transmembrane receptor ErbB2 overexpression is seen in a wide range of tumors, including breast and ovarian cancers." (PMID 39130630, 2024). "Supporting the role of NPC1 in invasion, 5 μM U18666A treatment of ErbB2 positive ovarian cancer organoids, whose invasive growth is dependent on full-length ErbB2, resulted in complete inhibition of invasive growth." (PMID 37420029, 2023). "The wet lab analysis of PRKCG SNP rs1331232028, like many other SNPs in multiple genes, including ERCC1, XPC, PIK3CA, ERBB2 and ERCC2, can be linked to ovarian cancer susceptibility." (PMID 36672978, 2023). "We redirected the CD19-CAR T cells against the ErbB2+ SKOV-3 ovarian cancer cells by adding the CD19-4D5scFv fusion protein." (PMID 36672182, 2023). "The team also synthesized AuNPs functionalized with a bio-inspired fusion protein carrier to target human epidermal growth factor receptor-2 (HER2) for ovarian cancer and simultaneously co-deliver doxorubicin and siRNA against erbB2." (PMID 38068916, 2023). "In conclusion, this study revealed a novel chemotherapeutic effect of baicalein on highly invasive ErbB2-positive ovarian cancer cells." (PMID 36770705, 2023). "The authors suggest that ZEB1 and FOXM1 are significant in ERBB2 signaling for peritoneal metastasis of ovarian cancer." (PMID 37324014, 2023). "This strategy enhances VEGF cell expression in ovarian cancer by upregulating increased ErBb2 expression, which in turn triggers a potent angiogenic response." (PMID 37845675, 2023). "In a previous study, we found that baicalein inhibited ErbB2-mediated malignant transformation of ErbB2-overexpressing ovarian cancer cells by downregulating ErbB2 gene expression at the transcriptional level (unpublished results)." (PMID 36770705, 2023). "On the other hand, the inhibition of ErbB2 expression in different ovarian cancer cell lines resulted in a significant increase of apoptosis evidenced by changes in caspase activity." (PMID 37312040, 2023). "An oncogenic synergy between PTP1B and HER2/ErbB-2 was observed in both breast and ovarian carcinomas." (PMID 37298571, 2023). "Other amplified oncogenes frequently found in epithelial ovarian cancer were ERBB2, STAT3, PIK3C2B, CDK2, and CDK4, as well as SWI/SNF chromatin modification complex genes, including ARID1A and SMARCC1." (PMID 36430324, 2022). "The rates of ERbB2 overexpression and/or amplification in ovarian cancer are variable, and while widely investigated, current attempts to target ERbB2 in ovarian cancer have been disappointing." (PMID 36140319, 2022).